GRID1 (glutamate ionotropic receptor delta type subunit 1)
Diseases named in the same sentence as GRID1 in open-access papers:
GRID1 is named in the same sentence as 49 diseases in open-access papers, as found by Europe PMC text mining. Sharing a sentence is not in itself a finding about the gene and the disease. The quoted sentences say what the papers report.
schizophrenia (21 papers, 2011 to 2026). A major psychotic disorder characterized by abnormalities in the perception or expression of reality. "The altered expression and genetic variations within GRID1 have been linked to schizophrenia pathology." (PMID 40779062, 2026). "miR-346 influences synaptic plasticity in schizophrenia primarily through its association with the GRID1 gene, which is involved in schizophrenia susceptibility." (PMID 40779062, 2026). "GRID1 encodes the glutamate receptor ionotropic δ1 subunit and plays a significant role in schizophrenia susceptibility due to its involvement in glutamatergic transmission." (PMID 40779062, 2026). "miR-346 is a microRNA located within the intron of the glutamate receptor ionotropic δ1 (GRID1) gene, which has been associated with schizophrenia susceptibility." (PMID 40779062, 2026). "Schizophrenia is strongly associated with glutamatergic dysfunction, wherein genes involved in glutamate signaling, such as GRID1, are key contributors to the disorder’s etiology." (PMID 40779062, 2026). "Based on genome-wide association studies, GRID1 was regarded as a strong candidate for schizophrenia with shared associations between schizophrenia and bipolar I disorder though a single-nucleotide polymorphism (SNP) genotyping screen." (PMID 41515947, 2025). "We performed a parallel assay for constitutive activity of the single GRID1 M3 variant found in the SCHEMA schizophrenia database, as well as three additional GRID1 M3 variants in presumably healthy individuals from the gnomAD database." (PMID 37944084, 2024). "Human GluD1 gene (GRID1) is a gene associated with susceptibility to schizophrenia, autism spectrum disorder, and depression." (PMID 32078638, 2020). "Genetic association studies have identified GRID1 as a susceptibility gene for psychiatric conditions, including schizophrenia, major depressive disorder, bipolar disorder, autism spectrum disorder, and alcohol dependence." (PMID 32234214, 2020). "The gene encoding GluD1 in humans (GRID1) is associated with a susceptibility for schizophrenia, major depressive disorder, and autism spectrum disorder." (PMID 32078638, 2020). "The coding sequence for pri-miR-346 is hosted in intron 2 of a known schizophrenia-susceptibility gene, glutamate receptor delta 1 subunit (GRID1)." (PMID 30470799, 2019). "The gene encoding miR-346 was located at the intron glutamate receptors ionic δ1 gene (GRID1), and the GRID1 gene is the susceptibility gene for schizophrenia." (PMID 28860957, 2018). "More generally, GRID1 has been associated at varying levels of significance with brain structure and schizophrenia." (PMID 28360924, 2017). "The gene encoding miR-346 is located in the intron of the glutamate receptor ionotropic δ1 (GRID1) gene, which is known to be involved in schizophrenia susceptibility." (PMID 25371713, 2014). "For example, Grid1, a subunit of the glutamate receptor, with polymorphisms associated with schizophrenia, was overexpressed in both the PFC and the STR of HIV-1Tg rats." (PMID 23536882, 2013). "Many of the GRID1 associated neuropsychiatric disorders such as schizophrenia and ASDs are also associated with unique cognitive deficits." (PMID 23560106, 2013). "Among the GRID1 associated disorders ASD has a very early onset at 2–3 years of age while others such as schizophrenia and bipolar disorder emerge in late teenage years and have been proposed to have a neurodevelopmental etiology." (PMID 23560106, 2013). "Since GRID1 gene has been found to be associated with schizophrenia we tested latent inhibition in GluD1 KO mice." (PMID 23560106, 2013). "Investigation revealed that miR-346, a miRNA that targets genes associated with schizophrenia, is encoded within the glutamate receptor ionotropic delta 1 (GRID1) gene which itself was shown previously to be a factor in schizophrenia susceptibility." (PMID 23805071, 2013).
schizophrenia (continued). "Genetic studies have shown a strong association of GRID1 gene with schizophrenia, mood disorders and ASDs." (PMID 23560106, 2013). "GRID1 gene is strongly associated with schizophrenia and ASD, disorders that are characterized by social deficits." (PMID 22412961, 2012). "Another deletion SCE 10q23.1 contains GRID1, which has been shown to be related with the increased risk of developing schizophrenia." (PMID 22815924, 2012). "As previously stated, the GRID1 gene that codes for GluD1 is strongly associated with mental disorders including schizophrenia, bipolar disorder, ASD and major depression." (PMID 22412961, 2012). "Genetic association studies have established the GRID1 gene, which codes for GluD1, as a strong candidate gene for schizophrenia, bipolar disorder, and major depressive disorder." (PMID 22412961, 2012). "Several single-nucleotide polymorphisms (SNPs) within the GRID1 gene have been identified as significantly associated with schizophrenia, suggesting that GRID1 may influence the risk of developing the disorder." (PMID 40779062, 2026). "Variations in GRID1, particularly in its promoter region, have been linked to structural changes in the brain, such as alterations in gray matter density in the anterior thalamus and prefrontal cortex, regions implicated in schizophrenia." (PMID 40779062, 2026). "There are evidences linking the variants of GRID1 with schizophrenia and bipolar disorder." (PMID 38075685, 2023). "Variations in the promoter region of the GRID1 gene have been associated with human schizophrenia." (PMID 25270331, 2014). "Furthermore, these findings are in agreement with the human genetic studies suggesting a strong association of GRID1 gene with several neuropsychiatric disorders including schizophrenia, bipolar disorder, autism spectrum disorders and major depressive disorder." (PMID 22412961, 2012). "The expression levels of miR-346 and GRID1 were found to be lower in the schizophrenia patients compared with the controls." (PMID 25371713, 2014). "Furthermore, the intron of the schizophrenia-susceptibility gene GRID1 encodes miR-346 which is down-regulated in schizophrenia, and based on target prediction algorithms preferentially targets genes which may be involved in the pathophysiology of this disorder." (PMID 22363537, 2012). "Quantitative qPCR studies have consistently demonstrated reduced miR-346 and GRID1 expression in schizophrenia patients, reinforcing the hypothesis that miR-346 plays a role in disease pathogenesis." (PMID 40779062, 2026). "The role of GRID1 in schizophrenia has been further supported by research showing connections between glutamatergic gene polymorphisms and white matter abnormalities, as well as elevated expression of white matter glutamate receptors in postmortem schizophrenia samples." (PMID 40779062, 2026). "In addition, we show that a GRID1 SCHEMA variant showed strong constitutive activity, consistent with a potential contribution to neuropathology in this patient and a role in schizophrenia." (PMID 37944084, 2024). "Interestingly, lower GRID1 mRNA expression is observed in the cerebral cortex of patients with schizophrenia and autism spectrum disorder." (PMID 32078638, 2020). "Because human mutations of the Grid1 gene are associated with schizophrenia, we next performed PPI of the acoustic startle response, which is one of the most promising electrophysiological endophenotypes of both patients and animal models of schizophrenia." (PMID 32078638, 2020). "To understand the variation that may disrupt gene function, we identified known missense, nonsense, and deletion variants in GRID1 and GRID2 from the public database ClinVar, the Schizophrenia Exome Sequencing Meta-analysis (SCHEMA) database, and published reports in the literature." (PMID 37944084, 2024).
bipolar disorder (6 papers, 2012 to 2024). A disorder of the brain that causes unusual shifts in mood, energy, activity levels and the ability to carry out day-to-day tasks. "Among the 5 genotypes associated with affective psychosis, CACNA1C and GRID1 were identified as common genes for bipolar disorder and depressive disorder, and CACNA1 was identified as the genotype most highly associated with affective psychosis." (PMID 38012695, 2023). "CACNA1C and GRID1 are common SNP genotypes for depressive disorder and bipolar disorder and should be considered associated with affective psychosis." (PMID 38012695, 2023). "Accordingly, CACNA1C and GRID1 were identified as common genes associated with both bipolar disorder and depressive disorder, suggesting that different types of psychosis not only have their own associated genes but also have common genes." (PMID 38012695, 2023). "Five SNPs were identified as associated with bipolar disorder and belonged to the CACNA1C, GRID1, and SIRT1 genotypes, with the majority belonging to the CACNA1C genotype." (PMID 38012695, 2023). "Accordingly, CACNA1C and GRID1 were identified as common genotypes for bipolar disorder and depressive disorder." (PMID 38012695, 2023). "Five SNPs were associated with bipolar disorder, namely rs541349080, rs7295590, and rs7979389 of the CACNA1C genotype; rs145322445 of the GRID1 genotype; and rs35648458 of the SIRT1 genotype." (PMID 38012695, 2023). "A total of 5 SNPs belonging to the CACNA1C, GRID1, and SIRT1 genotypes were significantly correlated with bipolar disorder (P < .001), with the majority belonging to the CACNA1C." (PMID 38012695, 2023). "Accordingly, the CACNA1C, GRID1, and SIRT1 genotypes were identified as carrying the highest risks of bipolar disorder." (PMID 38012695, 2023).
autism spectrum disorder (4 papers, 2012 to 2020). A spectrum of developmental disorders that includes autism, and Asperger syndrome. "Downregulation of GRID1 mRNA expression is also observed in iPS (induced pluripotent stem) cells derived from Rett syndrome patients, which is a condition associated with autism spectrum disorder." (PMID 32078638, 2020). "Interestingly, several genes (Adcyap1, Cntnap2, Grid1, Nrxn1, Nrxn3, Ucn, Tbx1, and Nr2e1), that are associated with disorders, stress response, social behaviors or autism spectrum disorders, are up-regulated specifically in the hippocampus of Del/+ mice." (PMID 28704368, 2017). "Copy number variation studies have also implicated GRID1 in autism spectrum disorder (ASD)." (PMID 22412961, 2012).
major depressive disorder (4 papers, 2012 to 2024). An episode of depression lasting two or more weeks without an intervening episode of mania. "While little is known about the phenotypic features of GRID1 human variants, GluD1 knock-out mice exhibit social deficits, in addition to anxiety-like, depression-like and aggressive behaviors." (PMID 37944084, 2024).
depression (3 papers, 2020 to 2024). "Eight SNPs were identified as associated with depressive disorder and belonged to the ANK3, BDNF, CACNA1C, and GRID1 genotypes, with the majority belonging to the ANK3 and CACNA1C genotypes." (PMID 38012695, 2023). "According to the generalized estimating equation analysis results, 8 single nucleotide polymorphisms (SNPs) belonging to the ANK3, BDNF, CACNA1C, and GRID1 genotypes were significantly correlated with depressive disorder (P < .001), with the majority belonging to the ANK3 and CACNA1C." (PMID 38012695, 2023). "Eight SNPs were associated with depressive disorder, namely rs142101917, rs191244436, and rs541490076 of the ANK3 genotype; rs193069165 of the BDNF genotype; rs116938681, rs188470158, and rs565998563 of the CACNA1C genotype; and rs558147168 of the GRID1 genotype." (PMID 38012695, 2023).
endometrial cancer (2 papers, 2020 to 2022). Primary or metastatic malignant neoplasm involving the endometrium (mucous membrane that lines the endometrial cavity). "The three LoF-intolerant genes (AKAP11, GRID1, and USP32) are all mutated in 5–8% of all Endometrial cancers in TCGA36." (PMID 35906355, 2022).
Rett syndrome (2 papers, 2020 to 2022). A severe neurodevelopmental disorder affecting the central nervous system. "Associated with metabolism pathways are DEGs related to metabolic syndromes like maturity-onset diabetes of the young 6 (NEUROD1), Sjogren-Larsson Syndrome (NXPH3), lipodystrophy (CAV1), and Rett Syndrome (GRID1)." (PMID 35883433, 2022).
Anosmia (1 paper, 2021). An inability to perceive odors. "In the case of ORF7b, its interaction with the glutamate receptor ionotropic delta-1 GRID1 and its interaction with ROBO2 a protein involved in the development of olfactory bulb neuron might explain the anosmia symptom in COVID-19." (PMID 33430309, 2021).
Ataxia (1 paper, 2024). Ataxia refers to impaired coordination of voluntary muscle movement. "Unlike GRID1 where phenotypes were variable, GRID2 missense and nonsense variants presented with ataxia (n = 20) and cerebellar atrophy (n = 6), consistent with the phenotypic characteristics of mutant Grid2 lurcher mice." (PMID 37944084, 2024).
colorectal cancer (1 paper, 2015). A primary or metastatic malignant neoplasm that affects the colon or rectum. "The aim of this study was to investigate the relationship between CHCHD3P1-HSP90AB7P, GRID1, HSPA12A, PRLHR, SBF2, POLD3, and C11orf93-C11orf92 genes and susceptibility to gastric and colorectal cancers in the Chinese Han population." (PMID 26302849, 2015). "The aim of this research was to study whether polymorphisms of CHCHD3P1-HSP90AB7P, GRID1, HSPA12A, PRLHR, SBF2, POLD3 and C11orf93-C11orf92 genes are associated with the risk of gastric and colorectal cancers in the Chinese Han population." (PMID 26302849, 2015).
folate deficiency (1 paper, 2020). A nutritional condition produced by a deficiency of FOLIC ACID in the diet. "Although our study did not include male mice, future investigation would be warranted to determine if folate deficiency was associated with an opposite transcriptional response (i.e., upregulation of Grid1) in those animals." (PMID 33282900, 2020).
keloid (1 paper, 2025). An irregularly shaped, elevated mark on the skin caused by deposits of excessive amounts of collagen during wound healing. "RNA-seq data revealed that GRIN2D was significantly upregulated in keloids compared to healthy controls, with other receptors like GRIA1 and GRID1 also showing notable expression changes." (PMID 41562114, 2025).
male pattern baldness (1 paper, 2020). "Out of 13 SNPs included in our predictive models for hair greying, 6 (FGF5 rs7680591, RUNX1 rs68088846, IRF4 rs12203592, BRINP1 rs2416699, TEX41 rs10928235, GRID1 rs2814331) were previously associated with male pattern baldness (MPB)." (PMID 32758128, 2020).
pulmonary hypertension (1 paper, 2014). Increased pressure within the pulmonary circulation due to lung or heart disorder. "These genes, such as PLA2G12A, RGCC, C9ORF3, GRIN2B, GRID1 and EPAS1, are involved in high-altitude physiology including angiogenesis, pulmonary hypertension, oxygen intake, defense response and erythropoiesis." (PMID 25270331, 2014). "Many genes are functionally related to high-altitude physiology, such as angiogenesis (RGCC), pulmonary hypertension remodeling (PLA2G12A), oxygen intake (C9ORF3), neural response (GRID1 and GRIN2B), melanin synthesis (MITF, PDGFRB and PIK3R3) and heart development (FOXS1, GAA and MYLK2)." (PMID 25270331, 2014).
sarcopenia (1 paper, 2020). Progressive decline in muscle mass due to aging which results in decreased functional capacity of muscles. "From the psoas muscle Hi-C dataset we identified unique druggable eGenes (e.g., GRID1, TNFRSF1A, STAT4) which represent potential therapeutic targets for treating the muscle wasting/weakness symptoms associated with NMD and sarcopenia." (PMID 32391060, 2020).
Stillbirth (1 paper, 2022). Death of the fetus in utero after at least 22 weeks of gestation. "GRID1 is known for its function in the central nervous system and is down-regulated in fetuses carrying deletion variants in PEG3 domain leading to stillbirth." (PMID 36238155, 2022).
psychiatric disorder (3 papers, 2012 to 2025). A disorder characterized by behavioral and/or psychological abnormalities, often accompanied by physical symptoms. "Additionally, we discuss its emerging clinical significance, with GRID1 mutations associated with neurodevelopmental and psychiatric disorders, and recent findings implicating GluD1 dysfunction in chronic pain." (PMID 41345253, 2025). "Besides GRID1, top markers mapped to within or near NPAS3, which potentially regulates genes involved in neurogenesis and has been previously associated with psychiatric disorders; and SV2B, a synaptic vesicle protein-encoding gene implicated in cognitive processes in model systems." (PMID 28360924, 2017).
neurological disease (1 paper, 2024). "This suggests a more localized intolerance to variation in this domain of GluD1 M3 compared to GluD2 and demonstrates a new functional mechanism by which GRID1 variants might trigger neurological disease." (PMID 37944084, 2024). "Here we present a comprehensive description of GRID1 and GRID2 variants that have been reported in individuals with neurological disorders, in addition to a number of newly described variants." (PMID 37944084, 2024).
GRID1 also shares sentences with these, for which no sentence is quoted: autism (4 papers); tumor (3); mood disorder (2); Obesity (2); albinism (1); alcohol dependence (1); amyotrophic lateral sclerosis (1); Anxiety (1); breast carcinoma (1); cardiovascular diseases (1); Cerebellar atrophy (1); COVID-19 (1); cryptorchidism (1); glaucoma (1); glioma (1); gout (1); hypospadias (1); Intellectual disability (1); Krabbe disease (1); lipodystrophy (1); maturity-onset diabetes of the young 6 (1); mental disorder (1); metabolic syndrome (1); microcephaly (1); Micropenis (1); oculocutaneous albinism type 1 (1); periodontitis (1); psychosis (1); Sjogren-Larsson syndrome (1); Spastic paraplegia (1).
A further 1 disease shares a sentence with GRID1 in 1 paper.